FANCF (FA complementation group F)
Diseases named in the same sentence as FANCF in open-access papers (continued):
Sharing a sentence is not in itself a finding about the gene and the disease.
breast carcinoma (continued). "FANCF might be a candidate target to develop novel therapeutic strategy to enhance response to topoisomerase II poisons in breast cancer." (PMID 22952942, 2012). "However, the effect of low expression of FANCF on sensitivity of breast cancer to drugs remains unclear." (PMID 22952942, 2012). "Therefore, we hypothesize that targeting the FA/BRCA pathway to inhibit DNA damage repair via inhibition of FANCF is vital for increasing the sensitivity to MX, the topoisomerase II poison in the breast cancer." (PMID 22952942, 2012). "In the present study, we show that specific short hairpin RNA (shRNA) decreases the levels of FANCF, mediates FA/BRCA pathway dysfunction, and potentiates the sensitivity of breast cancer to mitoxantrone through activation of JNK and p38 signal pathways." (PMID 22952942, 2012). "Our study shows that FANCF silencing in MCF-7 and T-47D breast cancer cells increases MX sensitivity by selectively inhibiting BCRP expression through activation of p38 MAPK pathway." (PMID 22952942, 2012). "In our present study, gene silencing of FANCF in MCF-7 and T-47D breast cancer cells blocked the FA/BRCA pathway as evidenced by reducing the level of FANCD2 mono-ubiquitination, the loss of FANCD2 foci, inhibiting cell proliferation, promoting apoptosis and DNA damage." (PMID 22952942, 2012). "ShRNA was used to knock-down FANCF expression in MCF-7 and T-47D breast cancer cells." (PMID 22952942, 2012). "Promoter hypermethylation is a well-known mechanism of transcriptional repression of tumor suppressor genes in breast cancer, including BRCA1, APC, CDH1, FANCF, among others, and may provide a complementary pathway of molecular carcinogenesis, independent of mutations." (PMID 33227964, 2020). "However, the functional role of FANCF in breast cancer has not been elucidated." (PMID 22952942, 2012). "The results showed that gene silencing of FANCF in MCF-7 and T-47D cells did not affect the protein expression of JNK, ERK, or p38, indicating that FANCF silencing in breast cancer cells did not activate the MAPK pathway." (PMID 22952942, 2012).
anemia (5 papers, 2021 to 2025). A reduction in the number of red blood cells, the amount of hemoglobin, and/or the volume of packed red blood cells. "Both a gene involved in the initial activation complex, Fanconi anemia complementation group F (FANCF), and genes involved in each of the end points of the pathway were found to contain SNPs." (PMID 33809122, 2021). "Additionally, we found a clique that consists of Fanconi anemia (FA) proteins (FANCF, FANCM, FANCG and FANCD2) and a third clique with two FA proteins together with BLM and RMI2." (PMID 38909016, 2024). "Interestingly, we found that 10 of 11 patients with lymphoma and another solid tumor harbored germline mutations in Fanconi anemia complementation group (FANC) genes, including FANCI, FANCA, FANCG, FANCL, FANCD1, FANCF, FANCJ, and FANCS." (PMID 37546421, 2023). "Furthermore, curcumin induces hypomethylation of Fanconi anemia (FANCF) promoter that leads to an increase in FANCF protein and gene expression in SiHa cells and a subsequent reduction in ovarian tumor cell proliferation." (PMID 36233012, 2022). "We also found that several Fanconi anemia (FA) proteins (e.g., FANCA, FANCF, FANCM, FANCD2), which are central proteins of inter-strand crosslink (ICL) repair, favored MMEJ." (PMID 38909016, 2024).
cervical cancer (5 papers, 2008 to 2023). A primary or metastatic malignant neoplasm involving the cervix. "Upon inhibiting M. SssI (DNMT1 analog), these two substances inhibited DNMT1, thereby hypomethylating and reactivating the FANCF promoter and inhibiting cervical cancer progression." (PMID 32328088, 2020). "Hypermethylated promoter of FANCF can be frequently detected in patients with cervical cancer." (PMID 32328088, 2020). "It is possible that strategies to re-express FANCF, might increase the sensitivity of such patients to standard treatment options for invasive cervical cancer." (PMID 31426393, 2019). "For example, FANCF gene is hypermethylated and repressed in cervical cancer cells." (PMID 31426393, 2019). "Promoter hypermethylation of FANCF gene could disrupt the FA-BRCA pathway, resulting in cisplatin resistance in cervical cancer." (PMID 34820332, 2021).
ovarian tumor (5 papers, 2008 to 2022). "For example, the FANCF deficient ovarian tumor cell line, 2008+vector cells exhibited an approximately a two- to three-fold decrease in survival as compared to the FA proficient 2008+FANCF cells to BCNU or TMZ." (PMID 21573016, 2011). "The laboratory proposed a model for ovarian tumor progression in which the initial methylation of FANCF was followed by FANCF demethylation, ultimately resulting in cisplatin resistance." (PMID 35582723, 2019). "Methylation of FANCF was demonstrated in 13.2% of 53 evaluable ovarian tumour samples." (PMID 18414472, 2008).
lung carcinoma (4 papers, 2008 to 2022). "ATM mutations and FANCF promoter-methylation are reported in lung carcinomas." (PMID 26438152, 2015). "Promoter hypermethylation of FANCF occurs in a significant proportion of lung cancer patients and is a significant predictor of poor survival." (PMID 26842001, 2016).
breast tumor (3 papers, 2012 to 2019). "The FA pathway has also been connected to TNBC, as comparison of mRNA expression in different breast tumor types revealed several FA pathway genes (BRCA1, FANCD2, FANCF, and PALB2) being significantly less expressed in TNBC tumors compared to luminal A (ER or PR positive) tumors." (PMID 28702895, 2017).
bladder cancer (2 papers, 2022 to 2023). "The high expression of ABCB9, SPTBN2, GULP1, IGF1, P4HB, NES and DPYSL2 and the low expression of ANXA6, OAS1, RAD9a, DNASE2B and FANCF would be beneficial to the prognosis of bladder cancer patients." (PMID 37845668, 2023).
myeloma (2 papers, 2021 to 2024). "Melphalan-resistant myeloma cell lines consistently express FANCF and RAD51C, which are involved in the FA/BRCA pathway for ICL repair, and depletion of FANCF overcomes melphalan resistance." (PMID 33525741, 2021). "The acquired melphalan-resistant myeloma cell line was found to express FANCF and RAD51C, which are involved in the FA/BRCA pathway and ICL repair." (PMID 33525741, 2021).
pancreatic cancer (2 papers, 2010 to 2020). "Additionally, we included FANCG and FANCF in these analyses, as FANCG represents another proximal FA gene that has been described to be mutated in GI cancer, specifically in pancreatic cancer, while FANCF has been reported to be epigenetically inactivated in various tumor types." (PMID 20509860, 2010).
squamous cell carcinoma (2 papers, 2015 to 2018). A carcinoma arising from squamous epithelial cells. "In line with the reported inactivation of the FA pathway through methylation of the FANCF promoter, down-regulation of FANCF RNA is identified in 5/212 lung squamous cell carcinomas in the publically available TCGA database." (PMID 26438152, 2015).
acute lymphoblastic leukemia (1 paper, 2025). Leukemia with an acute onset, characterized by the presence of lymphoblasts in the bone marrow and the peripheral blood. "For instance, high methylation of the FANCF (observed in a leukaemic CHRF-288 cell line), FANCC, and FANCL have been reported in a small portion of primary AML and acute lymphoblastic leukemia (ALL) cases." (PMID 40739565, 2025).
hereditary cancer (1 paper, 2020). Malignant neoplasms occurring in families at a rate greater than that expected by chance and caused by germline mutations in a specific gene. "A prospective cohort of 1021 unrelated cancer cases with clinical suspicion of hereditary cancer was screened for mutations in the following 14 FA genes: FANCA, FANCB, FANCC, FANCD2, FANCE, FANCF, FANCG/XRCC9, FANCI, FANCL/PHF9, FANCM, FANCP/SLX4, FANCQ/ERCC4, FANCR/RAD51 and FANCU/XRCC2." (PMID 32235514, 2020).
lung squamous cell carcinomas (1 paper, 2015). "Down-regulation of FANCF mRNA is present in only 5/212 lung squamous cell carcinomas (2 %) in the publically available TCGA database." (PMID 26438152, 2015). "Since inactivation of the FA pathway through methylation of the FANCF promoter was identified previously in 22 of 158 NSCLCs (14 %), we also examined mRNA expression levels for the FA genes in lung squamous cell carcinomas in the publically available TCGA database." (PMID 26438152, 2015).
non-small cell lung carcinoma (1 paper, 2015). A group of at least three distinct histological types of lung cancer, including non-small cell squamous cell carcinoma, adenocarcinoma, and large cell carcinoma. "Inactivation of the FA pathway through promotor methylation of FANCF was identified previously in 22 of 158 non-small-cell lung carcinomas (NSCLCs) (14 %)." (PMID 26438152, 2015). "Inactivation of the FA pathway through promotor methylation of FANCF was also identified previously in 22 of 158 non-small-cell lung carcinomas (NSCLCs) (14 %)." (PMID 26438152, 2015).
subependymal giant cell astrocytoma (1 paper, 2021). A benign, slowly growing tumor (WHO grade I) typically arising in the wall of the lateral ventricles and composed of large ganglioid astrocytes. "Furthermore, sequencing of three subependymal giant cell astrocytoma (SEGA)-like astrocytomas in NF1 mutant patients with ALT and intact ATRX have revealed genetic alterations in RECQL4, Fanconi anemia complementation group genes (FANCD2, FANCF, and FANCG), and SMARCAL1." (PMID 34069193, 2021).
cancer (24 papers, 2004 to 2025). A tumor composed of atypical neoplastic, often pleomorphic cells that invade other tissues. "BRCA1/2 somatic mutation or promoter methylation, ATM mutation, MRE11-dominant negative mutations in MMR-deficient cancers, FANCF promotor methylation and PTEN deficiency are all potential biomarkers of sensitivity to PARPi." (PMID 24616882, 2014). "In FANCF-deficient cancer cells, the repair of double-strand DNA break by homologous recombination is damaged, thus rendering the cancer cells highly sensitive to alternative double-strand break repair (DSBR) pathways, such as nonhomologous end-joining (NHEJ) single-strand annealing (SSA)." (PMID 22952942, 2012). "Thus, MX can be more toxic to FANCF-deficient cancers cells compared to healthy cells, since FANCF-deficient cancers lack the necessary DNA repair pathways that promote survival in healthy cells." (PMID 22952942, 2012). "Therefore, blockade of the alternative DSBR pathway in the FANCF-deficient cancers will indicate a synthetic lethal treatment for the FANCF-deficient cancers." (PMID 22952942, 2012). "For example, FANCF promoter was hypermethylated and had decreased expression in eight cancer types of BLCA, CESC, COAD, DLBC, ESCA, HNSC, UCEC, and UCS." (PMID 36497135, 2022). "Hypermethylation of tumor suppressor genes including MutL homolog 1 (MLH1), breast cancer 1 (BRCA1), FA complementation group F (FANCF), and checkpoint with forkhead and ring finger domains (CHER) is implicated in cancer development." (PMID 36307808, 2022). "The present finding along with the results from other cancer types suggests the presence of genomic instability due to the methylation mediated FANCF gene silencing." (PMID 15574200, 2004). "It is suggested that FANCF hypomethylation might lead to FANCF overexpression, disrupting the FA pathway and consequently contributing to cancer development." (PMID 40739565, 2025). "Thus, the FA/BRCA pathway, via FANCF, may represent a new target for preventing drug resistance and improving cancer treatment." (PMID 23440494, 2013). "Other known and possibly yet undiscovered cancer mechanisms are captured by the SKY92, including cell cycle pathways (BIRC5, TOP2A, and CENPE), cell growth and proliferation (FGFR3), DNA repair (FANCF, FANCI, POLQ), and transcription factor (STAT1)." (PMID 34448362, 2022). "Studies had shown that the overexpression of FANCF and FLT4 resulted in proliferation, migration, and invasion of cancer cells." (PMID 34642306, 2021). "Our previous studies found that the inhibition of FANCF blocked the functions of FA/BRCA pathway and enhanced antitumor drug sensitivity in cancer cells." (PMID 31511498, 2019). "Interestingly, our panel included genes already described to be cancer predisposition genes (FAS, ITK, KIF1B, PGR and MET) or previously reported as playing important roles in cancer (ABI1, ARID5B, DNMT3A, HEY1, KDM5C, NCOA1, NUP98, and SLC34A2), or in DNA repair process (FANCF)." (PMID 30925779, 2019). "FANCF interacts with BRCA1 and other proteins to initiate other cellular responses in the cancer cells." (PMID 28993682, 2017). "We examined the hypermethylation status of a panel of 5 normally unmethylated tumor suppressor or cancer genes: FHIT, FANCF, Cyclin-D2, BRCA2 and RUNX3 in 25 ovarian GCTs and ovarian cell line DNAs using the MSP assay." (PMID 15574200, 2004). "Similar frequencies of MLH1, BRCA1, and FANCF promoter methylation occurred in primary carcinomas without previous chemotherapy, after neoadjuvant chemotherapy, or in recurrent neoplasms." (PMID 19602291, 2009).
tumor (18 papers, 2004 to 2025). "These reversible changes in the methylation status further complicate the tumour assessment that shows the contribution of FANCF methylation." (PMID 15574200, 2004). "Finally, we examined TREX1 and FANCF levels in the tumour ECs from a xenograft GBM model and found significant downregulation of both at the RNA level." (PMID 27886180, 2016). "We found FANCF promoter hypermethylation in 24% of the tumours." (PMID 15574200, 2004). "When comparing tumor tissues to standard controls, a substantial upregulation of four genes was observed: CENPQ, YAE1, FANCF, and POC5." (PMID 41502527, 2025). "Analyses of 18 surgical HCC specimens yielded no further examples for genetic or epigenetic inactivation of FANCC, FANCF, or FANCG in HCC, suggesting a low prevalence of proximal FA pathway inactivation in this tumor type." (PMID 20509860, 2010). "The frequency of promoter hypermethylation of the tumor suppressor gene loci included in the panel was FHIT 28%, FANCF 24%, Cyclin-D2 12%, BRCA2 4%, and RUNX3 56% of the 25 tumours." (PMID 15574200, 2004). "Low expression of FANCF is known to lead to FANCD2 ubiquitin inactivation and dysfunction of the FA/BRCA pathway, which promote the sensitivity of tumor cells to DNA cross-linking agents, such as melphalan, cisplatin, and mitomyclin C in gliomas, myelomas, and ovarian cancers." (PMID 22952942, 2012). "Methylation of FANCF was seen more commonly in 85.7% of the serous subtypes compared with 65.7% of the nonserous tumours but this was not significant (P=0.32)." (PMID 18414472, 2008). "Thus, C-MET, CDKN2A, P-glyc (ABCB1) and N-cadherin displayed significantly lower protein expression levels in HGSOC tumors corresponding to PARPis-sensitive AsPCs, while FANCF and SPRY2 showed stronger expression in the PARPis-sensitive AsPCs-matched tumor samples." (PMID 33213473, 2020). "Finally, epigenetic inactivation of the proximal FA pathway via hypermethylation of FANCF has been reported in a variety of tumor entities, but its significance is not yet well understood." (PMID 20509860, 2010). "Therefore, the simultaneous inhibition of FANCF and REV1 is a theoretically valid strategy for sensitizing tumor cells to DNA-damaging agents and preventing the development of chemoresistance; however, one concern is that this combination may also lead to toxicity in some normal tissues." (PMID 31511498, 2019).
FANCF also shares sentences with these, for which no sentence is quoted: Fanconi anemia complementation group F (3 papers); depression (2); prostate carcinoma (2); acute myeloid leukemia (1); brain tumors (1); endometrial cancer (1); Fanconi anemia complementation group E (1); glioblastoma (1); granulosa cell tumor (1); head and neck cancer (1); hematologic malignancies (1); lung (1); lung adenocarcinoma (1); lymphoma (1); male infertility (1); melanoma (1); mesothelioma (1); systemic lupus erythematosus (1); testicular tumours (1); Tremor (1); xeroderma pigmentosum (1).